TBC1D1 (TBC1 domain family member 1)
Description:
May act as a GTPase-activating protein for Rab family protein(s). May play a role in the cell cycle and differentiation of various tissues. Involved in the trafficking and translocation of GLUT4-containing vesicles and insulin-stimulated glucose uptake into cells (By similarity).
Synonyms: KIAA1108; TBC; TBC1
Tractability: PROTAC: ubiquitination databases record sites on it; its protein half-life has been measured.
Safety:
Unwanted effects reported when the protein is acted on. In parentheses: how it was acted on, where the effect was seen, and who reports it.
less of a weight gain (source: ClinPGx)
weight gain (source: ClinPGx)
Gene: Protein-coding gene on chromosome 4 (37,890,836 to 38,139,175, forward strand). Ensembl gene ENSG00000065882.
Subcellular location: Nucleus
Subcellular location (Human Protein Atlas): Nucleoli
Pathways (Reactome):
Vesicle-mediated transport: Translocation of SLC2A4 (GLUT4) to the plasma membrane
Gene Ontology:
Molecular function: protein binding; GTPase activator activity
Biological process: regulation of cilium assembly
Cellular component: nucleolus; Golgi apparatus; nucleus
Genetic constraint (gnomAD): Loss-of-function variants: 83 observed, 115.92 expected, observed/expected ratio (o/e) 0.72, 90% interval 0.6 to 0.86. The upper end of that interval is the gene's LOEUF score, 0.86, which puts it in group 3 of 6, group 1 being the genes least tolerant of losing a copy. Missense variants: 1,322 observed, 1,451.4 expected, observed/expected ratio (o/e) 0.91, 90% interval 0.87 to 0.95. Synonymous variants: 542 observed, 560.08 expected, observed/expected ratio (o/e) 0.97, 90% interval 0.9 to 1.04.
Homologues: Orthologues: macaque TBC1D1 (98% identical), chimpanzee TBC1D1 (92% identical), dog TBC1D1 (91% identical), pig TBC1D1 (90% identical), mouse Tbc1d1 (90% identical), rat Tbc1d1 (90% identical), guinea pig TBC1D1 (89% identical), rabbit TBC1D1 (89% identical), tropical clawed frog tbc1d1 (68% identical), zebrafish tbc1d1 (55% identical). Paralogues in human: TBC1D4 (48% identical), TBC1D2 (13% identical), RABGAP1 (13% identical), RABGAP1L (13% identical), TBC1D2B (12% identical), TBC1D9B (12% identical), TBC1D9 (11% identical), EVI5L (11% identical), EVI5 (10% identical), TBC1D8 (10% identical), TBC1D10B (10% identical), TBCK (10% identical), and 33 more.
Diseases named in the same sentence as TBC1D1 in open-access papers:
TBC1D1 is named in the same sentence as 37 diseases in open-access papers, as found by Europe PMC text mining. Sharing a sentence is not in itself a finding about the gene and the disease. The quoted sentences say what the papers report.
Obesity (30 papers, 2009 to 2025). Accumulation of substantial excess body fat. "The TBC1D1-Ser231 KI mutation in mice gives rise to obesity and type 2 diabetes through promoting IGF1 secretion and thereby increasing lipogenesis in the adipose tissue." (PMID 35061665, 2022). "Protein‐coding SNVs in TBC1D4 and TBC1D1 have been associated with insulin resistance, obesity, and type II diabetes." (PMID 35579274, 2022). "It was shown that TBC1D1 variants are linked to obesity in many species, including human, rabbit and chicken, while deletion of murine Tbc1d1 suppressed obesity in ob/ob mice." (PMID 33769190, 2021). "Sequence variation in TBC1D1 is associated with growth- and obesity-related traits in pigs, chickens and rabbits as well as humans." (PMID 30135087, 2018). "TBC1D1 is linked to human obesity and TBC1D1 mutations in lean mouse confer leanness and protects from diet-induced obesity." (PMID 27467141, 2016). "For SNP Arg695Cys (rs58983546) in TBC1D1 we detected nominal association with obesity (pTDT = 0.03 in 705 trios)." (PMID 26828654, 2016). "The mutation led to resistance to diet-induced obesity and its causality for the phenotype was confirmed in Tbc1d1 knockout mice." (PMID 26828654, 2016). "In human beings, Tbc1d1 has been linked to familial obesity syndromes while in mice the loss of Tbc1d1 produces leanness and conveys resistance to diet induced obesity." (PMID 23967244, 2013). "The effect of the functional polymorphism R125W polymorphism in TBC1 domain family member 1 (TBC1D1) gene on severe obesity risk was restricted to females in French and US populations." (PMID 22043165, 2011). "We have recently shown that the normal Tbc1d1 allele reduces fatty acid oxidation in muscle, thereby enhancing obesity and diabetes susceptibility." (PMID 19578398, 2009). "Genetic studies have implicated that TBC1D1 is an important candidate gene of obesity." (PMID 35061665, 2022). "In addition, variation in TBC1D1 is associated with growth- and obesity-related traits in pigs, chickens and rabbits." (PMID 33087848, 2020). "TBC1D1 is associated with obesity-related traits and type 2 diabetes in both humans and mice." (PMID 33087848, 2020). "Polymorphism of TBC1D1 was found linked to the severe obesity in human." (PMID 28030618, 2016). "In particular, TBC1D1—which polymorphism has been related to several traits including glucose homeostasis, energy metabolism in skeletal muscle and blood, insulin resistance, adiposity, obesity, and type 2 diabetes —seems to reflect the directional selection occurred in HYB turkeys." (PMID 32751760, 2020). "TBC1D1 SNP Arg695Cys (rs58983546) could contribute to the obesity association of the gene." (PMID 26828654, 2016). "The TBC1D1 gene contributes to the development of obesity by regulating skeletal muscle insulin sensitivity." (PMID 35268233, 2022). "In mice, whole-body deletion of TBC1D1 confers leanness and protects against obesity induced by a high-fat diet." (PMID 35061665, 2022). "It is known that TDP-43 can regulate whole-body metabolism and glucose transport through the obesity-related gene TBC1 domain family member 1 (Tbc1d1)." (PMID 34200812, 2021). "The potential involvement of Arid5b in glucose metabolism through TBC1D1 would provide a new insight in the treatment of diabetes and obesity." (PMID 33023658, 2020). "It has been demonstrated that the deletion of TBC1D1 modifies glucose, lipid, and energy homeostasis impacting insulin resistance, body fat metabolism, leading to the development of obesity." (PMID 29882907, 2018). "Plx is the Drosophila ortholog of the related human Rab GAPs TBC1D1 and TBC1D4/AS160 that regulate the insulin-controlled traffic of the glucose transporter GLUT4 and have been linked to obesity." (PMID 25453831, 2014). "In addition, FOXO3 and TBC1D1 have been shown to be involved in lipid accumulation, fatty acid oxidation and obesity development." (PMID 36397714, 2023).
Obesity (continued). "There is suggestive evidence that this variant contributes to the obesity of the NZO strain, since the Lepr locus appeared to enhance the effect of the QTL Nob1 (later identified as Tbc1d1) on body weight and serum insulin in female (SJLxNZO)NZO backcross mice." (PMID 24752583, 2014). "Its homolog Tbc1d1 was linked to human obesity and a Tbc1d1 mutation underlies the absence of diet-induced obesity in the lean mouse strain." (PMID 24659297, 2014). "Recent genetic evidence from the Swiss Jim Lambert (SJL) mouse strain, which express a truncated form of the TBC1D1 protein, suggests that TBC1D1 may have a more direct role in whole-body energy homeostasis as these mice were lean and resistant to high fat diet-induced obesity." (PMID 23667688, 2013). "If TDP-43 knockouts showed decreases in skeletal muscle levels of Tbc1d1, a key regulator of glucose homeostasis and obesity, we hypothesized that TDP-43 over-expression might result in elevated steady state levels of Tbc1d1." (PMID 23967244, 2013). "Similarly, mouse models now substantiate that phosphorylation of TBC1D1 is a critical regulator of glucose uptake by the muscle, whereas HMGCR phosphorylation controls cholesterol levels, both of which contribute to the prevention of fatty liver disease and obesity." (PMID 39136185, 2024).
Insulin resistance (8 papers, 2011 to 2024). Increased resistance towards insulin, that is, diminished effectiveness of insulin in reducing blood glucose levels. "Activating AMPK improved insulin resistance in skeletal muscle through facilitating GLUT4 trafficking to the cellular membrane via phosphorylating TBC1 domain family member 1 (TBC1D1)." (PMID 34603021, 2021). "Our results provide further support for a role of the TBC1D1 PTB domains as a scaffold for a range of Rab regulators, and also the VPS13 family of proteins which have been previously linked to fasting glycaemic traits and insulin resistance in genome wide association studies." (PMID 33087848, 2020). "In skeletal muscle, the reduced GLUT4 expression in severe insulin resistance was associated with decreased ubiquitin-conjugating enzyme 9 (UBC9) expression while expression of GLUT1, TBC1D1 and AS160 was not significantly different among type 2 diabetic patients and matched controls." (PMID 22114711, 2011).
type 2 diabetes (7 papers, 2011 to 2023). "QTL mapping in the NZO mouse has identified Tbc1d1, Zfp69, and Lepr as genes contributing to type 2 diabetes." (PMID 36944993, 2023).
diabetes (4 papers, 2009 to 2024). "The present study showed that diabetes and exercise in warm water (35 °C) increased TBC1D1 and TBC1D4 compared to the healthy group." (PMID 38195613, 2024). "Thus, adiposity and diabetes in obese mice are modified by disruption of Tbc1d1 through a metabolic shift from glucose to fat oxidation." (PMID 24752583, 2014).
fatty liver disease (2 papers, 2022 to 2024). A reversible condition wherein large vacuoles of triglyceride fat accumulate in liver cells via the process of steatosis. "Here, to further explore the underlying role of AMPK-TBC1D1 signaling in hepatic steatosis, we detected NAFLD-related phenotypes in TBC1D1-KI mice at 4 to 6 months, 12 months, and 18 months of age." (PMID 35061665, 2022).
glioma (2 papers, 2024). A benign or malignant brain and spinal cord tumor that arises from glial cells (astrocytes, oligodendrocytes, ependymal cells). "The analysis revealed that elevated TBC1D1 expression in glioma is associated with an unfavorable prognosis and holds clinical diagnostic significance in predicting glioma outcomes." (PMID 38189823, 2024). "Our research also revealed that heightened TBC1D1 expression is closely linked to treatment resistance, compromising the effectiveness of immunotherapy and resulting in poor prognosis for glioma patients." (PMID 38529286, 2024). "The findings, as observed in the CGGA database, revealed an association between the prognosis of glioma patients and several factors, including high TBC1D1 expression, PRS type, and grade." (PMID 38189823, 2024). "We proceeded to investigate if heightened TBC1D1 expression independently serves as a risk factor impacting glioma prognosis." (PMID 38189823, 2024). "Univariate analysis showed that the prognosis of patients with glioma in the CGGA database was associated with the expression of TBC1D1, PRS type, histology, grade, age, and IDH mutations." (PMID 38189823, 2024). "Similarly, glioma patients with high-TBC1D1 tumors exhibited a higher frequency of mutations in IDH1." (PMID 38529286, 2024). "To explore the impact of TBC1D1 on the prognosis of individuals with glioma, we conducted an analysis using patient data retrieved from the CGGA and TCGA databases." (PMID 38189823, 2024). "Inhibition of TBC1D1 was found to potentially synergistically enhance the efficacy of immunotherapy and prolong the survival of cancer patients with gliomas." (PMID 38529286, 2024). "To achieve this goal, we will employ a combination of bulk and single-cell sequencing analysis to identify the specific function of TBC1D1 in glioma immunotherapy." (PMID 38529286, 2024). "The primary objective of this study is to comprehensively investigate the function and mechanism of TBC1D1 related to glioma’s immunotherapy resistance." (PMID 38529286, 2024). "This investigation introduces a novel perspective on TBC1D1’s involvement in tumorigenesis, highlighting its potential as a therapeutic target for addressing gliomas." (PMID 38189823, 2024). "A colony formation assay was conducted to assess the potential impact of TBC1D1 on glioma cell proliferation." (PMID 38189823, 2024). "In the context of glioma, despite its expression in numerous human cancers, previous research has paid little attention to the role of TBC1D1." (PMID 38529286, 2024). "This study marks the initial exploration of the impact of TBC1D1 on the progression of gliomas, with preliminary investigations." (PMID 38189823, 2024). "Immunohistochemical analysis validated higher TBC1D1 expression levels in tumor tissues, and a substantial increase in TBC1D1 expression was observed in the glioma cell line, 1321N1 compared to the normal cell line HA1800." (PMID 38529286, 2024). "A detailed exploration of the function and mechanism of TBC1D1 in glioma is crucial to gain fresh insights and develop strategies for treating the disease." (PMID 38529286, 2024). "Despite its significance in other cancer types, limited knowledge exists regarding the function of TBC1D1 in glioma, necessitating further investigation." (PMID 38529286, 2024). "This suggests that the expression level of TBC1D1 has credible value in predicting the prognosis of gliomas." (PMID 38189823, 2024). "The findings revealed a notable elevation in TBC1D1 levels in glioma patients over 40 years old compared to those under 40 years old." (PMID 38529286, 2024). "In this study, bioinformatics analysis was employed to identify TBC1D1 as a potential biomarker for the prognosis and immunotherapy of cancer patients with gliomas." (PMID 38529286, 2024). "In order to delineate the impact of TBC1D1 on the malignant behavior of glioma cells, we executed siRNA-mediated knockdown of TBC1D1 in both T98G and LN229 cell lines." (PMID 38189823, 2024).
glioma (continued). "Downregulation of TBC1D1 in glioma cells significantly inhibited multiple important functions, such as proliferation, migration, and invasion." (PMID 38189823, 2024). "To address this gap, we analyzed transcriptome data from various databases such as TCGA, GTEx, and GEO to explore the potential impact of TBC1D1 in glioma." (PMID 38529286, 2024). "Our research has revealed a significant positive correlation between TBC1D1 and IDH1 mutations in glioma patients, emphasizing the crucial involvement of TBC1D1 in modulating these mutations." (PMID 38529286, 2024). "Our aim is to thoroughly elucidate the involvement of TBC1D1 in glioma’s resistance to immunotherapy and provide substantial support for the development of more effective immunotherapeutic approaches." (PMID 38529286, 2024). "The findings indicated a notable upregulation of TBC1D1 expression in glioma tissues compared to normal tissues." (PMID 38529286, 2024). "In this study, the TBC1D1 gene exhibits elevated expression levels in tumor tissues and cells, particularly in glioma." (PMID 38529286, 2024). "The findings suggest that the diminution of TBC1D1 disrupts the cytoskeleton of glioma cells through the P-LIMK/cofilin pathway, consequently influencing the migratory behavior of tumor cells." (PMID 38189823, 2024). "Our observations revealed that the attenuated expression of TBC1D1 exerted a suppressive influence on malignant phenotypic traits, comprising the intricate processes of glioma proliferation, invasion, and migration." (PMID 38189823, 2024). "The ROC curve was established to verify the expression of TBC1D1 in glioma tissues and the results of the database analysis." (PMID 38189823, 2024). "Specifically, our analysis will focus on the expression levels of TBC1D1 in glioma and its relevance to tumor immunotherapy response." (PMID 38529286, 2024). "Additionally, we will examine the impact of TBC1D1 on tumor immune evasion and drug resistance to uncover its mechanism in glioma." (PMID 38529286, 2024). "In summary, TBC1D1 exerts influence on the structural integrity of the cytoskeleton via its interaction with cofilin, leading to morphological alterations and changes in the aggressiveness of glioma cells." (PMID 38189823, 2024). "Expression of TBC1D1 in glioma cell lines was detected by western blotting." (PMID 38189823, 2024). "This, in turn, triggers actin depolymerization upon downregulation of TBC1D1 in glioma cells." (PMID 38189823, 2024). "Hence, to scrutinize the potential involvement of TBC1D1 in the migration and invasion of glioma cells, transwell and wound healing assays were conducted." (PMID 38189823, 2024). "An analysis of treatment outcomes in glioma patients from the TCGA database revealed a strong association between high TBC1D1 expression and non-responsive patients." (PMID 38529286, 2024). "The results showed that high TBC1D1 expression may be an important factor in the poor prognosis of gliomas." (PMID 38189823, 2024). "Additionally, TBC1D1’s impact on glioma likely involves a complex interplay of multiple clinically relevant factors." (PMID 38529286, 2024). "The levels of TBC1D1 were significantly elevated in tumor tissue from glioma patients." (PMID 38529286, 2024). "In addition, the study identified the concurrent expression of 10 genes alongside TBC1D1 in gliomas, implying their potential contribution to tumor development." (PMID 38529286, 2024). "In investigating this hypothesis, we attenuated the expression of TBC1D1 within glioma cell lines." (PMID 38189823, 2024). "Overall, the study results indicated that macrophages with elevated TBC1D1 levels may play a crucial role in immunotherapy resistance and can act as a compelling biomarker when predicting the chances of survival for patients with gliomas." (PMID 38529286, 2024).
glioma (continued). "Therefore, we posited that TBC1D1-positive macrophages could inhibit the effectiveness of immunotherapy in glioma patients, leading to immunotherapy tolerance and poor prognosis." (PMID 38529286, 2024). "Blocking TBC1D1 could minimize immunotherapy resistance in cancer patients with gliomas." (PMID 38529286, 2024). "There was no significant change in the expression of E-cadherin, however, the expression of N-cadherin, MMP-2, and MMP-9 decreased, further indicating that the downregulation of TBC1D1 affected the MMP family and thus weakened the aggressiveness of gliomas." (PMID 38189823, 2024). "The results of this study suggest that the knockdown of TBC1D1 affects the downstream expression of MMP2 and MMP-9 and inhibits the invasiveness of glioma cells." (PMID 38189823, 2024). "Our findings clearly indicated that high TBC1D1 expression impairs favorable prognosis in the context of high CTL function in tumor tissues, leading to poor survival outcomes among glioma patients." (PMID 38529286, 2024). "In our investigation of the relationship between TBC1D1 and the TME, scRNA-seq data from glioma obtained from the GEO database were analyzed." (PMID 38529286, 2024). "To advance our comprehension of the impact of TBC1D1 on the TME, we conducted transcriptome sequencing analysis on single cells obtained from glioma patients in the GEO database." (PMID 38529286, 2024). "The expression of TBC1D1 proteins was also increased in the SVG and glioma cell lines (U87, U118, T98G, U251, and LN229), especially in T98G and LN229 cells." (PMID 38189823, 2024). "However, the role of TBC1D1 in glioma-genesis remains unclear." (PMID 38189823, 2024). "We further demonstrated that the tumor-inhibitory effect of TBC1D1 might occur through the P-LIMK/cofilin pathway, destroying the cytoskeletal structure and affecting the depolymerization of F-actin, thereby inhibiting glioma migration." (PMID 38189823, 2024). "However, there are no studies on the correlation between TBC1D1 expression and glioma prognosis." (PMID 38189823, 2024). "Stratifying glioma patients into two groups based on their TBC1D1 levels, it was observed that patients with elevated TBC1D1 levels exhibited high macrophage infiltration within the TME, while a noticeable negative correlation was observed between TBC1D1 and T cell infiltration levels." (PMID 38529286, 2024).